NRF1 (nuclear respiratory factor 1)
Diseases named in the same sentence as NRF1 in open-access papers (continued):
Sharing a sentence is not in itself a finding about the gene and the disease.
cancer (continued). "The first genome-scale analysis of transcription factor binding sites in cancer found that binding by transcription factors such as Sp1, NRF1, and YY1 could protect CpG island gene promoters from cancer-specific hypermethylation." (PMID 25994056, 2015). "Our findings imply that under physiological settings of ADT, a long-term shift in the Nrf1 and Nrf2 balance in cancer cells may result in enhanced AR function in a subpopulation of cells and enable the outgrowth of CRPC." (PMID 24466341, 2014). "The ability of both Nrf1 and AR to respond to oxidative stress signaling and to regulate differentiation processes suggests that Nrf1 and AR might also be able to interact during differentiation in normal development or possibly during cancer progression." (PMID 24281119, 2010). "Here we provide evidence that suggests that the Nrf1 and Nrf2 transcription factors may regulate the expression of antioxidant proteins that modulate hormone receptor signaling in cancer cells." (PMID 24281119, 2010). "We hypothesize that cancer cells modify the balance of Nrf1 and Nrf2 signaling and expression to create a favorable environment in which oxidative stress, due to changes in antioxidant expression, can continually be used to enhance cell growth." (PMID 24281119, 2010). "We have discussed the role of the Nrf1 and Nrf2 transcription factors and role of the antioxidant enzymes Prx-1 and Txn-1, as mediators of hormone receptor signaling in cancer cells, possibly via their chaperone activities and/or transcription factor activation functions." (PMID 24281119, 2010). "The combined activities of Nrf1 and Nrf2 protect cells during cellular stresses and may enable both normal and cancer cells to survive in toxic environments." (PMID 24281119, 2010). "Thus, NatA/E and proteasomal genes are co-regulated in both cancer and non-cancer cells, with NRF1 being one potential factor underlying this coordination." (PMID 38864963, 2025). "NRF1 inhibition sensitizes cancer cells to proteasome inhibitors, suggesting that the suppression of NRF1 activity may have a synergizing effect with proteasome inhibitors for the treatment of cancer patients exhibiting elevated proteasome activities." (PMID 33535386, 2021). "However, NRF1 antagonizes the effect of proteasome inhibitors on cancer cell growth through the proteasome bounce back response, suggesting that the suppression of NRF1 activity sensitizes cancer cells to these compounds." (PMID 33535386, 2021). "In addition to the O-GlcNAc-regulated network, the results from motif enrichment and ChIP-seq signal distribution analyses implied that NRF1 is a master regulator that is necessary for complex transcriptome changes and maintains the homeostasis of cancer cells during exposure to genotoxic stress." (PMID 33214551, 2020). "Our findings reconcile the paradoxical role of mitochondria in tumor formation and also imply that interventions blocking hypoxic suppression of NRF1 may contribute to therapeutic strategies in curing cancer by reactivating immunity and sensitizing the tumor cells to apoptotic stimuli." (PMID 30833558, 2019). "Furthermore, reduction of NRF1 was also found significantly correlated with cancer progression." (PMID 30833558, 2019). "Recently, it was reported that Nrf1 stability is also regulated by O-linked N-acetylglucosamine (O-GlcNAc) modifications in serine or threonine residues by the O-linked N-acetylglucosamine transferase (OGT), an enzyme that is highly active in many types of cancer." (PMID 31295808, 2019). "However, this cannot explain how NRF1 drives breast tumorigenesis because p16-deficient MCF-10A cells do not form malignant tumors." (PMID 30486409, 2018). "Drp1 overexpression significantly elevates ROS and the expression levels of PGC1-α and Nrf1/2, which subsequently promote ESCC cancer growth." (PMID 40528181, 2025).
cancer (continued). "Nrf1, NGLY1, and DDI2 are co-essential in some cancer cell lines, suggesting that Nrf1-dependent regulation of the proteasome promotes proliferation of cancer cells." (PMID 38991033, 2024). "In accordance, ATF1 is positively correlated with both pluripotent (33/33, 23/33 of cancer types for MYC and NANOG, respectively) and mitochondrial regulators (33/33 of cancer types for both TFAM and NRF1) in TCGA cohorts." (PMID 37463926, 2023). "In the Myc datasets (GSE22139, GSE11791), multiple top-ranked TFs, such as MAX, SP1, NRF1, and E2F4, are known to interact with MYC in regulating the expression of common target genes in cancer cells." (PMID 38032891, 2023). "In cancer cells, NRF3 has also been shown to suppress NRF1 translation through the cytoplasmic polyadenylation element binding protein 3 (CPEB3)." (PMID 36359002, 2022). "Individual NRF1, NRF2 and NQO1 expression within all cancer, immune and stromal cells are heterogenous in this closely-related cohort." (PMID 36359002, 2022). "NRF1 activation also promotes EMT and produces cancer stem cells, thus facilitating the metastatic process." (PMID 36230841, 2022). "While the emCpGs harbour enriched binding sites for their specific emTFs, the non-correlated CpGs shared a binding signatures for SP1, CTCF, NRF1, GABPA, KLF9, and YY1 providing a protective effect against de novo methylation across cancer types." (PMID 35440061, 2022). "An important metabolite that activates NRF1 is UDP-GlcNAc (uridine diphosphate N-acetylglucosamine), which is abundantly generated in many cancer cells from glucose and glutamine via the hexosamine pathway." (PMID 33535386, 2021). "Recently, researchers have found Tomm34 is transcriptionally regulated by NRF-1 and NRF-2 under cancer stress and hyperactive condition during metabolic reprogramming." (PMID 34257607, 2021). "As analyzed above, distinct subset of DEGs regulated by Nrf1, TCF11 and/or Nrf2 were annotated for their functional relevancies to cancer development or prevention." (PMID 34268128, 2021). "It is very plausible that NRF1 activity is regulated by UDP-GlcNAc synthesis, which is often enhanced in cancer cells." (PMID 33535386, 2021). "Highly expressed CD47 levels are present in multiple types of cancers including solid tumors and hematologic malignancies, which is major regulated by some transcription factors such as NFκB, Myc, HIF-1 and NRF-1." (PMID 34512146, 2021). "In cancer cells, while NRF2 confers therapeutic resistance via increasing antioxidant capacity and modulating glucose and glutamine metabolism, NRF1 confers therapeutic resistance via triggering proteasome bounce back response." (PMID 33535386, 2021). "Overall, the data presented here bring new insights into nelfinavir’s multiple activities in cancer cells and identify nelfinavir as the first inhibitor to inhibit TCF11/Nrf1 proteolytic activation." (PMID 32344880, 2020). "NRF1 and NRF3 complimentarily sustain basal proteasome activity in cancer cells, indicating a functional redundancy between NRF3 and NRF1, as described in Section 2.7." (PMID 32962187, 2020). "We have also revealed NRF3 translationally represses NRF1 by inducing the CPEB3 gene, which maintains basal proteasome activity in cancer." (PMID 32962187, 2020). "While investigating the biological relationship between NRF3 and proteostasis in cancer, we discovered one more regulatory mechanism—cross talk between NRF3 and NRF1 in colon cancer cells." (PMID 32962187, 2020). "Evidence has shown that overexpression of TIGAR in carcinoma cells increases the expression of PGC-1α, NRF1, MitoNEET, and Tomm20, which are important markers of mitochondrial biogenesis and OXPHOS32." (PMID 30814486, 2019). "Collectively, the phenotypic differences in the morphology of between Nrf1+/+ and Nrf1α−/− cells indicate a possibility that Nrf1α-specific knockout may promote the epithelial-mesenchymal transition (EMT), a process entailing a considerable risk of cancer transformation." (PMID 27065079, 2016).
cancer (continued). "In the present study, we also observe that in response to chemotherapy, Nrf1 and Nrf2-mediated signalling is reactivated in MCF7 cancer cells in contact with stromal fibroblasts." (PMID 25915429, 2015). "The sensitivity of cancer cells actively expressing both NRF1 and EZH2 to EZH2i is significantly greater than that of cancer cells actively expressing individual EZH2 or NRF1 alone and much greater than that of cancer cells expressing low levels of EZH2 and NRF1." (PMID 42140904, 2026). "Active NRF1 and EZH2 expression may be a useful combined predictor for the treatment of cancers with EZH2is." (PMID 42140904, 2026). "Modulating Nrf1 function via fine-tuning N-glycosylation could also be exploited therapeutically, as blocking Nrf1 processing has been proposed as a strategy to enhance the efficacy of proteasome inhibitor drugs, such as BTZ, in cancer treatment." (PMID 40623109, 2025). "They confirmed that NETs could confer a rapid tumor growth and a higher expression of PGC-1α, NRF1 and TFAM, as well as increased levels of mitochondrial density, mtDNA, ATP production and oxygen consumption rate (OCR) in cancers." (PMID 39273403, 2024). "Upon activation by norepinephrine, ATF1 potentiates cancer stemness by coordinated trans-activation of both nuclear pluripotency factors MYC/NANOG and mitochondrial biogenesis regulators NRF1/TFAM, thereby orchestrating nuclear reprograming and mitochondrial rejuvenating." (PMID 37463926, 2023). "Furthermore, the interplay between NRF1 and E2F4 transcription factors was previously shown to contribute to cancer development and progression." (PMID 37627157, 2023). "With upstream regulation of NRF1 by adenosine 5’-monophosphate (AMP)-activated protein kinase (AMPK), pharmacological activation of AMPK in cancer cell lines led to an upregulation of TERRA, thereby suggesting a link between cellular fitness and telomere metabolism." (PMID 36057868, 2022). "NRF1 mediates drug resistance in cancer via an oncometabolite, UDP-GlcNAc, which stimulates proteasome subunit genes in response to proteasome inhibitors, before maintaining proteasome activity and protecting cancer cells from proteotoxicity." (PMID 35969177, 2022). "Besides, NRF1 up-regulated E2F1 expression transcriptionally, then orchestrated both c-MYC and E2F to regulate their target genes for cancer proliferation." (PMID 35448958, 2022). "NRF1+NQO1−NRF2− cancer cell populations were not indicative of improved patient survival probability (p = 0.15)." (PMID 36359002, 2022). "NQO1 expression was not correlated to paired NRF1 or NRF2 expression in cancer, immune or stroma cells, contrary to studies proposing NRF1- or NRF2-directed adaptive response upon NQO1 transcription in mice and human keratinocytes." (PMID 36359002, 2022). "Thus, as a regulator of NRF1, OGT is a promising target for use in combination with proteasome inhibitors as an anti-cancer therapy." (PMID 33535386, 2021). "It remains unclear whether and how NRF1 and NRF3 regulate proteasome activity cooperatively in cancer cells." (PMID 33535386, 2021). "Many cancer cells exhibit increased levels of glucose and glutamine uptake, leading to an abundant synthesis of UDP-GlcNAc that fuels OGT-mediated O-GlcNAcylation and the subsequent accumulation of NRF1 protein and the facilitation of the proteasome pathway." (PMID 33535386, 2021). "However, an experimental approach is needed to verify the cooperation between H2A.Z and TFs such as SP2, ZNF384, YY1, NRF1, and NFYA in the transcriptional misregulation in cancer." (PMID 35317119, 2021). "Therefore, NRF1 maintains a 26S proteasome activity for normal development, whereas NRF3 alternatively maintains 20S proteasome activity for cancer development through both POMP-20S proteasome and CPEB3-NRF1 axes." (PMID 34884489, 2021).
cancer (continued). "Notably, basal expression of Nrf1 in distinct HCC tissues had been shown significantly altered, relative to the equivalent expression in their adjacent para-carcinoma tissues or those expressed in normal liver cells." (PMID 34268128, 2021). "The prognostic significance of the major redox regulator nuclear factor erythroid-2-related factor (NRF2) is recognized in many cancers, but the role of NRF1 is not generally well understood in cancer." (PMID 31687076, 2019). "Regarding mitochondrial metabolism, the interaction between ERα and its natural ligand 17β-estradiol promotes the transcription of NRF-1, which in turn activates mitochondrial biogenesis and mitochondrial oxygen consumption in low-metastatic breast MCF-7 and lung H1793 cancer cells." (PMID 31600993, 2019). "Further, these findings suggest that the human homolog of Ebd, Jerky (also known as JRK or JH8), and the human homolog of Ewg, Nuclear respiratory Factor 1 (NRF1), may provide promising drug targets for the treatment of Wnt-driven cancers." (PMID 29615557, 2018). "Previous works had shown that NRF1, in link with members of the PGC-1 family of co-activators, promotes mitochondrial biogenesis and activity, including in cancers, suggesting a role cancer metabolism." (PMID 29968728, 2018). "Our discovery of the interaction between NRF1 and the OGT/HCF-1 complex has added a new regulatory axis to the proteasome bounce-back response and identified OGT as a new therapeutic target for sensitizing cancer cells to proteasome inhibitors." (PMID 29941490, 2018). "Intriguingly, two TFBS motifs (ZNF263 and NRF1) had significantly increased relative PWM-scores in cancer compared to 1KG, suggesting binding is enhanced in cancers, and raising the possibility of adaptive evolution at these particular classes of binding sites in cancer." (PMID 27490693, 2016). "Almost equal amounts of Nrf1 and TCF11 are detected to be co-expressed in some normal human cell lines, whilst human cancer cell lines express predominantly Nrf1 rather than TCF11 (data not shown)." (PMID 26268886, 2015). "The NDR promoters, unlike the NP promoters, were enriched for binding motifs for specific transcription factors such as SP1 and NRF1, typical “housekeeping” transcription factors that normally protect CGI promoters from methylation in both normal and cancer cells." (PMID 25747664, 2015). "Furthermore, it was found that genistein inhibits cancer cells through modulating the expression of certain transcription factors, such as STAT-3, Nrf1, Nrf2, AP-1 and CREB." (PMID 19742137, 2009). "Without all the facts, NRF1 might play a certain role in cancer oxidative stress both directly and indirectly." (PMID 35448958, 2022). "Averaged fluorescent signal intensities of NQO1, NRF1 and NRF2 from the whole cohort were plotted using Spearman’s correlation coefficient, which demonstrated no correlative relationship between NQO1 and NRF1 (r = 0.002) or NQO1 and NRF2 (r = −0.161) expression in cancer cells." (PMID 36359002, 2022). "However, it is not clear about a role of Nrf1 in mediating the cancer cellular response to metabolic stress, especially stimulated by glucose deprivation." (PMID 32774674, 2020). "We propose that metabolic reprogramming of cancers allows highly expressed OGT to maximally contribute to O-GlcNAcylation and to eventually develop dependence on the UPS and resistance to proteasome inhibitors by enhancing NRF1-mediated transcriptional activation of proteasome subunit genes." (PMID 29941490, 2018). "The mechanism by which NRF1 may reprogram adult breast epithelial cells to acquire cancer stem cell properties is not clear." (PMID 30486409, 2018). "However, although much attention has been focused on the role of Nrf2 in cancer, investigations on the role of Nrf1 has been severely lacking." (PMID 24466341, 2014).
cancer (continued). "Moreover, ssGSEA analysis with transcription factor gene sets in 1019 human cancer cell lines (The Cancer Cell Line Encyclopedia, CCLE dataset) indicates that CRE transcription factor (ATF1 and CREB1) activities are positively correlated with MYC targets, NRF1 targets and stemness scores." (PMID 37463926, 2023). "However, NRF3 is highly expressed in many cancer cells, implying that the proteasome in cancer or normal cells is maintained through the CPEB3-NRF1 axis or the negative feedback regulation of NRF1." (PMID 34884489, 2021). "Thus, in cancer cells, OGT is likely to exert its full activity without being restricted by substrate limitation, which would positively correlate the OGT protein level with the O-GlcNAcylation activity, the NRF1 protein level, and the expression levels of proteasome subunit genes." (PMID 29941490, 2018).